PXN (paxillin)
Diseases named in the same sentence as PXN in open-access papers (continued):
Sharing a sentence is not in itself a finding about the gene and the disease.
cerebrovascular diseases (1 paper, 2024). "Our findings suggest that targeting paxillin could be a promising therapeutic strategy for treating cardiovascular and cerebrovascular diseases caused by abnormal VSM contraction." (PMID 38254202, 2024). "Our findings revealed a previously unknown role for paxillin in the SPC-induced abnormal contraction of VSM, highlighting its potential as a therapeutic target for reducing cardiovascular and cerebrovascular diseases associated with abnormal VSM contraction." (PMID 38254202, 2024).
ciliopathy (1 paper, 2023). A genetic disorder of the cellular cilia or the cilia anchoring structures, the basal bodies, or of ciliary function. "This led us to hypothesize that the OFD1 domain responsible for binding to paxillin may differ from the one involved in ciliopathy." (PMID 38139355, 2023).
colorectal tumor (1 paper, 2015). "We thus suggest that anti-apoptosis and invasiveness concomitantly mediated by PXN overexpression may play a critical role in colorectal tumor progression and metastasis." (PMID 25826088, 2015). "Interestingly, PXN expression was positively correlated with Bcl-2, pBcl-2-S87, and MMP2 expression in colorectal tumors." (PMID 25826088, 2015).
COVID-19 (1 paper, 2022). A disease caused by infection with severe acute respiratory syndrome coronavirus 2. "Based on bioinformatics analysis and previous studies, this study identified hub genes (RPS7, IGF1R, DICER1, ERH, MCTS1, TNPO1, FLNA, and PXN) that may contribute to the evaluation and treatment of COVID-19 and thrombosis." (PMID 35692833, 2022).
diffuse large B-cell lymphoma (1 paper, 2021). "PXN expression was downregulated in lymphoid neoplasm diffuse large B-cell lymphoma (DLBC), thymoma, and uterine carcinosarcoma (P < 0.01)." (PMID 34135128, 2021).
dystroglycanopathy (1 paper, 2019). "We previously determined that either NAD+ supplementation or overexpression of Paxillin are sufficient to improve muscle structure and the myomatrix in a zebrafish model of primary dystroglycanopathy." (PMID 31391079, 2019). "Here, we show that muscle phenotypes in a zebrafish model of FKRP-associated dystroglycanopathy are improved with NAD+ supplementation but not Paxillin overexpression." (PMID 31391079, 2019). "However, whether Paxillin concentration at the MTJ is disrupted in zebrafish models of secondary dystroglycanopathy and whether Paxillin overexpression ameliorates muscle degeneration in zebrafish models of secondary dystroglycanopathy have not been investigated." (PMID 31391079, 2019).
Fever (1 paper, 2024). Body temperature elevated above the normal range. "The results indicate that K3OR treatment can have an antipyretic effect by downregulating PXN expression in the mouse model of LPS-induced fever." (PMID 38611918, 2024). "During the process of LPS-induced fever, Toll-like receptor 4 (TLR4), the receptor for LPS, is upregulated on the cell membrane through paxillin-mediated mechanisms." (PMID 38611918, 2024).
fibrosarcoma (1 paper, 2020). A malignant mesenchymal fibroblastic neoplasm affecting the soft tissue and bone. "Vinculin, paxillin, talin, zyxin, VASP, FAK, p130Cas, and alpha-actinin appear diffuse in human fibrosarcoma cells within 3D gels, while py-paxillin appears diffuse in MDA-MB-231 cells within confined microchannels." (PMID 32390868, 2020).
gastric adenoma (1 paper, 2014). A neoplastic polyp that arises from the stomach. "The expression of paxillin was significantly more highly expressed in gastric adenoma than in non-neoplastic mucosa and carcinoma (P<0.05)." (PMID 24348846, 2014). "Statistically, paxillin expression was increased in gastric adenoma in comparison with that in the non-neoplastic mucosa and carcinoma." (PMID 24348846, 2014). "Paxillin was highly expressed in gastric adenoma compared with that in non-neoplastic mucosa and carcinoma (P<0.05)." (PMID 24348846, 2014).
head and neck cancer (1 paper, 2008). A primary or metastatic malignant neoplasm affecting the head and neck. "Several reports identify paxillin as an inducer of metastasis; for instance, in head and neck cancers that have metastasized to lymph nodes paxillin expression is increased." (PMID 18492274, 2008).
HIV-1 infection (1 paper, 2023). The type species of lentivirus and the etiologic agent of acquired immunodeficiency syndrome (AIDS). "On other hand, VCL is dispensable for integrin-mediated uptake of S. aureus, and due to its negative effect on paxillin phosphorylation, VCL blocks the early stages of HIV-1 infection." (PMID 37023213, 2023).
Hyperglycemia (1 paper, 2025). An increased concentration of glucose in the blood. "FYN interacts with proteins like nephrin and paxillin during hyperglycemia and impacts cytoskeleton and cell adhesion in podocytes." (PMID 41011980, 2025).
Hypertension (1 paper, 2021). The presence of chronic increased pressure in the systemic arterial system. "Recent research suggested that PXN (paxillin) is involved in hypertension, but this gene might be associated with progression of T1D in patients with obesity." (PMID 33827531, 2021).
inflammatory bowel disease (1 paper, 2025). A spectrum of small and large bowel inflammatory diseases of unknown etiology. "PXN has also been implicated in several inflammatory and immune-related diseases, including rheumatoid arthritis and inflammatory bowel disease, as well as tumor-associated inflammation." (PMID 41357518, 2025).
inflammatory breast carcinoma (1 paper, 2020). An advanced, invasive breast adenocarcinoma characterized by the presence of distinct changes in the overlying skin. "We identified cyclin D1 at the plasma membrane in inflammatory breast cancer, and cyclin D1 colocalized to the cytoplasmic membrane with PACSIN II and Paxillin (Y118) in MRC-5 cells." (PMID 32948740, 2020).
intestinal-type carcinoma (1 paper, 2014). "Kaplan-Meier analysis indicated a positive association between paxillin expression and cumulative survival rate in all, advanced and intestinal-type carcinoma patients (P<0.05)." (PMID 24348846, 2014).
invasive carcinoma (1 paper, 2013). A carcinoma that is not confined to the epithelium, and has spread to the surrounding stroma. "Paxillin expression was found to correlate with HER-2 gene amplification in 314 cases of invasive carcinoma, which led to speculation about whether paxillin might be a marker that could influence the predictive value of HER-2 regarding the response to adjuvant treatment." (PMID 23657508, 2013).
keloid (1 paper, 2023). An irregularly shaped, elevated mark on the skin caused by deposits of excessive amounts of collagen during wound healing. "Additionally, IL-6 treatment of normal fibroblasts increased paxillin alignment, while tocilizumab treatment of keloid fibroblasts decreased paxillin alignment, showing that this response was downstream of IL-6 signaling." (PMID 37660739, 2023). "However, immunostaining for paxillin, a marker of mature focal adhesions, which are thought to be the primary structures responsible for force-transmission to the ECM, highlighted a highly aligned network of cell-matrix adhesions in keloid fibroblasts." (PMID 37660739, 2023).
laryngeal carcinoma (1 paper, 2025). Carcinoma that arises from the laryngeal epithelium. "Key genes like CDC42, PXN, ITGB1, PGK1, SLC2A1, ISG15 and ICAM1, affected by HPV, display distinct functional alterations and complex correlations in laryngeal cancer progression." (PMID 40821990, 2025). "PXN, ITGB1, ISG15, SLC2A1 and ICAM1 are regarded as potential therapeutic targets for HPV-positive laryngeal cancer." (PMID 40821990, 2025). "ISG15, ITGB1, PXN, SLC2A1 and ICAM1 are expected to become potential therapeutic targets for HPV-positive laryngeal cancer." (PMID 40821990, 2025). "PXN and PGK1 are expected to be potential prognostic markers for HPV-positive laryngeal cancer." (PMID 40821990, 2025). "PXN and PGK1 are considered as potential prognostic markers for HPV-positive laryngeal cancer." (PMID 40821990, 2025).
leiomyosarcoma (1 paper, 2014). An uncommon, aggressive malignant smooth muscle neoplasm, usually occurring in post-menopausal women. "However, no suppression of either FAK or paxillin phosphorylation, two key regulators of tumor cell migration, could be observed for both leiomyosarcoma cell lines (data not shown)." (PMID 25340839, 2014).
leukocyte adhesion deficiency (1 paper, 2025). Leukocyte adhesion deficiency (LAD) is a primary immunodeficiency characterized by defects in the leukocyte adhesion process, marked leukocytosis and recurrent infections. "The critical role of paxillin in immunocyte trafficking is underscored in pathological conditions such as leukocyte adhesion deficiency (LAD), a genetic disorder characterized by defective integrin-mediated adhesion and the migration of leukocytes." (PMID 40001476, 2025).
liver fibrosis (1 paper, 2023). "Highlighted Article: Paxillin is shown to be a key molecule important in the function of fibrosis effector cells, which emphasizes a novel role for it in liver fibrosis and cirrhosis, a leading cause of morbidity and mortality worldwide." (PMID 37667902, 2023). "Collectively, these results imply that paxillin is a key regulator in the fibrogenic response that underlies liver fibrosis." (PMID 37667902, 2023). "We believe that understanding the role of paxillin on other phenotypes of HSC activation is crucial for gaining a complete understanding of its role in liver fibrosis." (PMID 37667902, 2023). "Taken together, these findings highlight paxillin as a novel potential therapeutic target for liver fibrosis." (PMID 37667902, 2023). "Not only does this study shed new light on the cell biology of paxillin and fibrogenic effector cells, but it also highlights paxillin as a potential target for future therapeutic approaches in liver fibrosis." (PMID 37667902, 2023). "Finally, overexpression of paxillin in vivo stimulated liver fibrosis, and its deletion from HSCs in a novel conditional knockout mouse decreased liver fibrosis." (PMID 37667902, 2023). "In summary, we have demonstrated a novel role for paxillin in HSC activation and liver fibrosis." (PMID 37667902, 2023). "This raises the possibility that paxillin potentiates liver fibrosis rather than initiates it." (PMID 37667902, 2023).
lymphoma (1 paper, 2019). A malignant (clonal) proliferation of B- lymphocytes or T- lymphocytes which involves the lymph nodes, bone marrow and/or extranodal sites. "Sialylation may lead to a more invasive phenotype of lymphoma cells through integrin‐Rho‐paxillin collaboration." (PMID 31317621, 2019).
metastatic melanoma (1 paper, 2021). A melanoma that has spread from its primary site to another anatomic site. "Searching for an alternative strategy to inhibit the oncogenic activity of FAK, we show that inhibiting FAK scaffolding function using a small peptide altering FAK–paxillin interactions reduces both migration and invadopodia-mediated matrix degradation in metastatic melanoma cells." (PMID 33919725, 2021).
nephrotic syndrome (1 paper, 2019). A collection of symptoms that include severe edema, proteinuria, and hypoalbuminemia; it is indicative of renal dysfunction. "Interestingly, enhanced expression of paxillin and FA kinase have been reported in glomeruli of rat models of glomerular immune injury and in experimentally induced nephrotic syndrome, while modulation of paxillin activity and FA formation appear as a putative therapeutic target for podocytopathies." (PMID 31816967, 2019).
odontogenic cyst (1 paper, 2024). A cyst in the jaw that arises from tissues of tooth development. "The lack of difference between PXN expression and the patterns of biological behavior of odontogenic lesions suggests that the over-expression of PXN may occur in carcinomas and not in odontogenic cysts and tumors." (PMID 38962075, 2024). "Hence, it seems that targeting PXN has no clinical importance for treatment and lessening the destruction and extension of surgeries in invasive odontogenic cysts and tumors." (PMID 38962075, 2024).
oral cancer (1 paper, 2024). "In conclusion, the study offers compelling evidence supporting salivary paxillin as a reliable biomarker for oral cancer, emphasizing its potential clinical significance in early diagnosis and prognosis while advocating for further research to validate its broader diagnostic utility." (PMID 39048985, 2024). "This investigation was carried out to analyze and compare the salivary paxillin levels between oral potentially malignant disorders (OPMDs), OSCC and the healthy controls to assess its potential role as a biomarker of oral cancer aiming for early diagnosis and better prognosis of OSCC." (PMID 39048985, 2024). "Besides, they also concluded that the advanced expression of paxillin, FAK, and MMP-11 could strongly increase the incidence of oral cancer metastasis." (PMID 39048985, 2024).
ovarian tumor (1 paper, 2021). "All these data suggest that ECM1a, but not ECM1b, induces ovarian tumor growth, most likely through the AKT/FAK/Paxillin/Rac signaling axis." (PMID 34244494, 2021).
paraganglioma (1 paper, 2021). A benign or malignant neoplasm arising from paraganglia located along the sympathetic or parasympathetic nerves. "PXN expression positively correlated with the infiltration level in BRCA, kidney renal papillary cell carcinoma, LGG, pheochromocytoma and paraganglioma, and thymoma." (PMID 34135128, 2021). "However, PXN expression was downregulated in BRCA, COAD, kidney renal papillary cell carcinoma, LUAD, LUSC, UCEC, and pheochromocytoma and paraganglioma." (PMID 34135128, 2021).
Portal vein thrombosis (1 paper, 2012). Thrombosis of the portal vein and/or its tributaries, which include the splenic vein and the superior and inferior mesenteric veins. "Our results are consistent with previous studies that demonstrated that paxillin and FAK overexpression, as well as their phosphorylation, were associated with low differentiation in the presence of portal vein thrombosis, along with extra-hepatic metastasis, all synonyms of high malignancy in HCC." (PMID 22937161, 2012).
renal clear cell carcinoma (1 paper, 2021). "We found that the PXN mRNA level was downregulated in renal clear cell carcinoma (RCC), LUAD, BRCA, COAD, and UCEC (P < 0.001) compared with levels in normal tissue controls." (PMID 34135128, 2021).
Salmonella Infections (1 paper, 2013). Infections with bacteria of the genus SALMONELLA. "Interestingly, our microarray study showed that FA proteins such as Paxillin are up-regulated immediately after Salmonella infection." (PMID 23826261, 2013).
sarcoma (1 paper, 2011). A usually aggressive malignant neoplasm of the soft tissue or bone. "Regardless, exogenous galectin-3 led to decreased phosphorylation of FAK and loss of phosphorylated paxillin from the focal adhesion complexes, favoring sarcoma cell migration." (PMID 22216245, 2011). "We have also observed a decrease in the amount of phosphorylated paxillin upon exposure of sarcoma cells to galectin-3." (PMID 22216245, 2011).
schizophrenia (1 paper, 2016). A major psychotic disorder characterized by abnormalities in the perception or expression of reality. "Our findings indicate possible global defects in cell motility, which provides a platform for testing the roles of specific proteins, such as paxillin or talin, components of focal adhesions, in reelin-associated deficits in schizophrenia." (PMID 27602387, 2016).
schwannoma (1 paper, 2018). A benign, usually encapsulated slow growing tumor composed of Schwann cells. "We proved that fMLP and CpG ODN act as prototypic mtDAMPs and modulate the outgrowth of cytoplasmic processes of RT4 schwannoma cells in association with increased levels of phosphorylated paxillin." (PMID 30542268, 2018).
small cell lung carcinoma (1 paper, 2009). Small cell lung cancer (SCLC) is a highly aggressive malignant neoplasm, accounting for 10-15% of lung cancer cases, characterized byrapid growth, and early metastasis. "As an example, in small cell lung cancer (SCLC), activation of MET with HGF leads to phosphorylation/activation of several pathways involving cell proliferation/survival (ERK1/2, AKT), cell cycle (RB), and cytoskeletal proteins (paxillin, FAK)." (PMID 19955662, 2009).
Stroke (1 paper, 2022). Sudden impairment of blood flow to a part of the brain due to occlusion or rupture of an artery to the brain. "Similar downregulation of PXN by Diphenyleneiodonium for the treatment of stroke has been also documented although experimental evidence describing functional pathways of PXN involvement in stroke pathology is scarce." (PMID 35250546, 2022).
uterine carcinosarcoma (1 paper, 2021). A usually aggressive malignant neoplasm arising from the uterine corpus and less often the cervix. "The mutation frequency of the PXN gene in patients with uterine carcinosarcoma is nearly as high." (PMID 34135128, 2021).
uterine tumors (1 paper, 2021). "PXN has the highest mutation frequency in patients with uterine tumors (nearly 5%)." (PMID 34135128, 2021).
Yersinia infection (1 paper, 2024). "The other was “Yersinia infection, oas05135”(p = 0.078788), containing 5 genes (MAP3K7, PXN, DOCK1, LOC101103376, and LOC101103623) and is also associated with immunity." (PMID 38333624, 2024).